SIRT3 (sirtuin 3)
Diseases named in the same sentence as SIRT3 in open-access papers (continued):
Sharing a sentence is not in itself a finding about the gene and the disease.
tumor (continued). "Using the established SIRT3 knockdown or SIRT3 overexpressing gastric epithelial cells to investigate the role of SIRT3, we confirmed results from previous studies that suggested that SIRT3 functions as a tumor suppressor due to the suppression of ROS-mediated HIF-1α activation." (PMID 29108235, 2017). "As a key regulator of different cancers, SIRT3 detoxifies ROS to act as a tumor suppressor." (PMID 27686535, 2017). "In addition, SIRT3 exerts its tumor suppressive function by repressing ERK1/2, increasing Bax and/or activating caspase-3." (PMID 27483432, 2016). "Up to date, oncogenic and tumor-suppressive roles of SIRT3 were observed in cancers." (PMID 27483432, 2016). "The mechanism for SIRT3 as a tumor promoter can be explained by the fact that SIRT3 might engage in cross-talk with Fas/receptor-interacting protein (RIP)/focal adhesion kinase (FAK) death–survival pathways in cancer cells." (PMID 27483432, 2016). "Downregulation of SIRT3 in HCC cells facilitates tumor cell survival." (PMID 27367026, 2016). "Furthermore, the prognostic finding that patients with higher expression of SIRT3 had shorter overall survival in our meta-analysis also reveal that SIRT3 function as tumor promoter after cells have been completely transformed." (PMID 27483432, 2016). "However, SIRT3 is also found to express in some human tumors; its role in these SIRT3-expressing tumor cells needs to be elucidated." (PMID 26121691, 2015). "Our data, however, support a hypothesis whereby SIRT3 acts primarily as a tumour suppressor, possibly by promoting apoptosis, a function which may be lost in more aggressive malignancies." (PMID 26121130, 2015). "In vivo, OA also suppresses tumor growth through destabilizing HIF1α and upregulating SIRT3." (PMID 25855962, 2015). "As HIF1α stimulates the expression of glycolytic enzymes and decreases reliance on mitochondrial oxidative phosphorylation in tumor cells, we speculated that OA may regulate glycolysis via SIRT3 through a process involving HIF1α." (PMID 25855962, 2015). "Conversely the dysregulated tumour cells may be unable to increase activation of SIRT3, resulting in continued aerobic glycolysis, enhanced proliferation and sensitivity to chemotherapy." (PMID 26121130, 2015). "However, some tumor cells show the expression of SIRT3 and the potential role of SIRT3 in these tumor cells, especially its potential relation to the aggressive phenotype, has been controversial." (PMID 26121691, 2015). "The mechanisms of SIRT3 promoting tumor cell survival may be due to increased cell proliferation, migration, and invasion as suggested by our in vitro study." (PMID 25105144, 2014). "Studies have also shown that SIRT3 downregulation reduced tumor burden in vivo." (PMID 25105144, 2014). "Discrepancy of the role of SIRT3, however, has been described as a tumor suppressor in mouse." (PMID 25105144, 2014). "However, it should be pointed out that recent work links an extra copy of the SIRT3 gene with a tumor-prone phenotype in humans." (PMID 25085992, 2014). "On one hand, some studies revealed that SIRT3 is a tumor promoter that prompts tumorigenesis." (PMID 25105144, 2014). "In consistent with this hypothesis, we found that the decreased expression level of intratumoral Sirt3 could independently predict elevated risks of tumor recurrence and patients’ death." (PMID 24774224, 2014). "SIRT3 is the only member that has been associated with longevity in human and has been identified as a cell survival factor protecting cells from genotoxic stress through utilizing the mitochondrial NAD pool in tumor cells." (PMID 25105144, 2014). "Moreover, we demonstrated that the down-regulation of Sirt3 in HCC indicated aggressive tumor behaviors and predicted an unfavorable clinical outcome." (PMID 24774224, 2014).
tumor (continued). "In addition, we performed the in vitro study to unfold the effects of SIRT3 on the biological behaviors, including proliferation, apoptosis, migration, and tumor invasion, of cultured colon cell lines." (PMID 25105144, 2014). "In addition, overexpression of SIRT3 is shown to decrease tumorigenesis in xenografts, even when induction of SIRT3 occurs after tumor ignition." (PMID 23800187, 2013). "In addition, a key role of SIRT3 in mitochondria is to serve as a mitochondrial localized tumor suppressor via its ability to inhibit mitochondrial ROS production." (PMID 23800187, 2013). "Furthermore, MEFs with Sirt3−/− were easily immortalized by infection with a single oncogene, and developed into subcutaneous xenograft tumor in nude mice once expressing Myc or Ras." (PMID 23272146, 2012). "Future study is directed to mechanistically understand how and whether SIRT3 exerts its tumor suppressor function by inactivating the Skp2 oncogenic pathway solely in a deacetylase-dependent manner." (PMID 23230084, 2012). "SIRT3 decreased ROS and maintained genomic stability to act as a tumor suppressor." (PMID 23272146, 2012). "Strikingly, low SIRT3 expression could also predict poor overall survival of HCC patients with tumor size (<5 cm), grade (I-II), or stage (I-II)." (PMID 23272146, 2012). "We further demonstrate that the SIRT3 tumor suppressor interacts with and deacetylates Skp2, suggesting that targeting Skp2 or the p300/SIRT3 axis could be a novel approach for the treatment of human cancers, especially those with up-regulation of Skp2." (PMID 23230084, 2012). "Sirt3 functions as a tumor suppressor and maintains mitochondrial integrity during cellular stress." (PMID 23236377, 2012). "Decrease of SIRT3 in HCC was significantly correlated with clinical stage, serum AFP level, tumor differentiation and tumor multiplicity, indicating that SIRT3 might be involved in HCC progression." (PMID 23272146, 2012). "Moreover, we found that the SIRT3 tumor suppressor serves as the physiological deacetylase that antagonizes p300-mediated Skp2 acetylation." (PMID 23230084, 2012). "In addition, SIRT3 has been proposed as tumour suppressor via its ability to suppress ROS and regulate HIF-1α thus inhibiting tumour growth." (PMID 22666258, 2012). "SIRT3 reduces oxidative stress, a major source of cellular and genomic damage, and may function as a gate-keeping tumor suppressor." (PMID 21307404, 2011). "The Sirt3−/− MEFs were also immortalized and transformed by infection with a single oncogene suggesting that Sirt3 might function as an in vitro tumor suppressor." (PMID 22016654, 2011). "The increased expression of SIRT3 seen in lymph node-positive tumours may, therefore, contribute to survival of these more aggressive tumours." (PMID 17003781, 2006). "However, SIRT3 serves as a tumor suppressor in certain types of cancer." (PMID 40777993, 2025). "Importantly, UTMD-mediated SIRT3 delivery also effectively suppressed tumor growth in vivo." (PMID 41471349, 2025). "Moreover, SIRT3 can reprogram metabolism, significantly impacting tumor initiation and progression." (PMID 39944690, 2025). "Moreover, we showed that high expression of SIRT3 in GBM predicted poor prognosis, implying that SIRT3 might inhibit tumor cell death by acting as an oncogene in GBM." (PMID 38395990, 2024). "The tumor suppressor or oncogene action of SIRT3 may depend on the tumor type and context." (PMID 38395990, 2024). "Additionally, the effect of SIRT3 on tumor immunity has been little studied." (PMID 39501597, 2024). "Interestingly, SIRT3 may play a dual role in tumorigenesis and progression by acting as an oncogene or a tumor suppressor depending on its targets." (PMID 37507016, 2023). "Moreover, our results demonstrated that matrine and berberine improved the expression of Sirt3, which could inhibit growth of tumor cells." (PMID 37404762, 2023).
tumor (continued). "Treating DEN rats with GaNPs and low dose of γ-radiation significantly elevated Sirt-3 expression which may play a role in tumor suppression, mainly through mediating the suppression of hypoxia-inducible factor 1α (HIF-1α) and inhibiting mitochondrial ROS production." (PMID 35776276, 2022). "Notably, downregulation of miR-1225-5p and upregulation of miR-224 may promote tumor cell growth, proliferation, and metastasis via targeting SIRT3 directly in thyroid cancer and non-small cell lung cancer cells." (PMID 35832551, 2022). "Similarly, SIRT3 knockdown promoted cell division and thus tumor growth." (PMID 36499440, 2022). "However, depending on the cell type and tumor type, SIRT3 may function as either oncogene or tumor suppressor." (PMID 35326523, 2022). "Thus, GA treatment might lead to an abnormal cell energy metabolism by SIRT3 inhibition, thereby blocking tumor proliferation." (PMID 34747319, 2022). "Therefore, SIRT3 can act as a tumor suppressor in OSCC cell lines." (PMID 35571098, 2022). "As a tumor suppressor, downregulation of SIRT3 may promote a Warburg phenotype." (PMID 35832551, 2022). "Here, we set out to identify downstream signals induced by SIRT3 deficiency in DLBCL cells to gain insight into how SIRT3 could interface with nutrient flux stress response pathways to support proliferation of DLBCL cells and promote tumorigenesis in this particular tumor context." (PMID 35019856, 2022). "Moreover, the GA treatment could significantly decrease the weight of xenograft tumor tissues and its SIRT3 protein levels in vivo, while SIRT3 overexpression reversed these effects." (PMID 34747319, 2022). "Similarly, SIRT3 may also regulate tumor metabolism reprogramming by modulating tumor cell glycolysis." (PMID 35832551, 2022). "The selection of SIRT3 activators/inhibitors in combination with chemotherapeutic agents may offer a potential approach to cancer treatment to prevent the formation of a microenvironment conducive to tumor recurrence." (PMID 35832551, 2022). "Interestingly, most studies have shown that SIRT3 could promote cancer metastasis, which may be closely related to the SIRT3-mediated tumor cell metabolism reprogramming and the EMT." (PMID 35832551, 2022). "It has been demonstrated that SIRT3 expression was induced in a number of radiation-treated human cancer cells and xenografts, and it was showed that enhanced SIRT3 transcription and posttranslational modifications contributed to adaptive radioresistance in tumour." (PMID 33069104, 2021). "Furthermore, SIRT3-mediated mitophagy protects tumor cells against apoptosis under hypoxia." (PMID 33790896, 2021). "Moreover, SIRT3 plays a role in monitoring the stability of tumor genomes." (PMID 32724473, 2020). "Importantly, inhibition of SIRT3 has a significant impact on tumor progression." (PMID 33273545, 2020). "Thus, the modulation of SIRT3 might be a novel treatment in patients with HCC and, possibly, other cancers in which SIRT3 acts as a tumor suppressor." (PMID 32306906, 2020). "Consequently, SIRT1 and SIRT3 are important regulators of tumour cell survival and cell function in the tumour microenvironment, with SIRT1 overexpression in mesenchymal stem cells (MSC) enhancing NK cell attraction, thereby shifting MSC effects from potentiating to supressing tumour progression." (PMID 33375613, 2020). "However, whether SIRT3 functions as a tumor promoter or suppressor in apoptosis remains controversial, and further studies will be needed to confirm this hypothesis." (PMID 31817470, 2019). "However, the involvment of SIRT3 in regulating diet-dependent tumor development is obscure." (PMID 31970087, 2019). "Finally, SIRT3 was shown to drive both pro-tumorigenic and tumor-suppressive effects." (PMID 31849939, 2019). "In addition, knock-out animal studies demonstrate a tumor suppressor function for SIRT3." (PMID 29099803, 2017). "SIRT3 may drive both oncogenic and tumor-suppressive effects." (PMID 28634345, 2017).
tumor (continued). "Therefore, the role of SIRT3 in neoplasia is cell type-specific, and potentially quite complex." (PMID 27367026, 2016). "Therefore, Sirt3 acts as a fidelity protein and a tumor suppressor gene within the mitochondria." (PMID 27023612, 2016). "In addition, acetylation of nicotinamide mononucleotide adenylyltransferase 2 (NMNAT2), decreased Tam-induced apoptosis and/or increased Ku70-Bax interaction may also contribute to the tumor promoter role of SIRT3." (PMID 27483432, 2016). "Finally, due to lack of available data, the association between SIRT3 and other important clinical parameters such as tumor infiltration and recurrence were not able to be explored." (PMID 27483432, 2016). "Furthermore, the mitochondrial tumour suppressor Sirtuin 3 promotes destabilization of HIF1α." (PMID 25974097, 2015). "There has been continuing debate as to whether SIRT3 acts as a tumour promoter or suppressor." (PMID 26121130, 2015). "Such molecular mechanism underlying the suppression of tumor by SIRT3 has not been reported before." (PMID 26317998, 2015). "In addition to destabilizing c-MYC as reported herein, SIRT3 could function as a tumor suppressor possibly via its ability to deacetylate the proto-oncogene Skp2." (PMID 26317998, 2015). "Thus, the function of SIRT3 varies in normal and tumor tissues and may be cell- and tumor-type specific." (PMID 25105144, 2014). "Moreover, SIRT3 has tumor suppressive functions and reduces the glycolytic metabolism." (PMID 25221980, 2014). "On the other hand, some studies showed that SIRT3 may be a tumor suppressor." (PMID 25105144, 2014). "In this study, we found that SIRT3 gene mutations were present in both OECM-1 and HSC-3 cell lines, and in OSCC patients, supporting the hypothesis that SIRT3 may act as a tumor suppressor and regulate the initiation and progression of cancer by controlling cellular redox balance." (PMID 23800187, 2013). "We found that the SIRT3 proteins from OSCC patients had significantly lower deacetylase activity than SIRT3 proteins from normal subjects, thus suggesting that a decrease of SIRT3 activity may increase susceptibility to tumor development." (PMID 23800187, 2013). "Thus, SIRT3 is emerging as a care-taking tumor suppressor that may alleviate aging and prevent cancer." (PMID 21307404, 2011). "Finally, it also seems clear that Sirt3 is a mitochondrial localized tumor suppressor or fidelity protein and identifying the downstream deacetylation targets of Sirt3 will lead to better understanding of mechanism linking mitochondrial fidelity, carcinogenesis, and aging." (PMID 22016654, 2011). "Thus, six years ago we, and others, constructed mice lacking the mitochondrial Sirt3 gene to determine if Sirt3 is a fidelity gene and if loss of function would create an in vivo tumor permissive phenotype." (PMID 22016654, 2011). "Sirtuin 3 (SIRT3, a human homologue of SIR2) is a mitochondrial NAD-dependent deacetylase that functions as an oncogene in some cancers and as a tumor suppressor gene in other cancers." (PMID 40298644, 2025). "Sirtuin 3 (SIRT3), a mitochondrial delactylase, is expressed in HCC and acts as a tumor suppressor by promoting apoptosis and inhibiting tumor growth." (PMID 40948941, 2025). "Further studies revealed that, upon targeting the mitochondria of tumor cells, Mito-ICT-4 downregulated SIRT3 protein expression, disrupted intracellular redox homeostasis, and markedly increased mitochondrial ROS levels." (PMID 40333582, 2025). "Meanwhile, the HIF-1α/ROS regulatory axis couples the SIRT3- and SIRT6-driven metabolic reprogramming to oxidative adaptation and glycolytic flexibility, enabling tumor cells to maintain mitochondrial function and survive cytotoxic insults." (PMID 41425553, 2025). "While SIRT3, SIRT4, and SIRT6 are poised to induce tumor-suppressive autophagy, others, such as SIRT2 and SIRT7, are likely to stimulate protective autophagic programs that underlie tumor survival and drug resistance." (PMID 41425553, 2025).
tumor (continued). "Mechanistically, SIRT3 was shown to bind to and downregulate hypoxia-inducible factor-1α (HIF-1α), a key transcription factor involved in angiogenesis and tumor progression." (PMID 41471349, 2025). "FKBP9L and CCDC108 were found to be significantly increased in tumor tissues, whereas the expression of KRT20, ZFAND2A, and SIRT3 was significantly decreased in tumors." (PMID 40406545, 2025). "Jin and colleagues proved that SIRT3 suppresses HCC development by delactylating cyclin E2 (CCNE2), a lactylated substrate of SIRT3, thereby reducing its ability to promote tumor growth in HCC cells." (PMID 40720394, 2025). "Conversely, pharmacological activation of SIRT3 under acidic extracellular pH promotes mitochondrial carbonic anhydrase VB (CAVB) activation and autophagy, supporting cell survival in harsh tumor microenvironments." (PMID 41471349, 2025). "Mechanistically, ALKBH5 inhibits ACC1 deacetylation by promoting SIRT3 methylation, and the resulting downregulation of ACC1 expression ultimately inhibits tumor growth, lipid metabolism, and tumorigenesis." (PMID 39759516, 2024). "To further demonstrate the antagonizing role of SIRT3 against GBM ferroptosis in vivo, we tested the tumor inhibition effects of targeting SIRT3 before inducing ferroptosis." (PMID 38395990, 2024). "Mitochondrial deacetylases, Sirtuin-3 (SIRT3), and SIRT1 are enzymes found within the mitochondria that actively promote the proliferation and migration of tumor cells." (PMID 38302953, 2024). "SIRT3 inhibition by miRNA-708-5p in PDAC leads to enhanced glycolysis, increased oxidative stress and diminished autophagy, all of which promote tumor growth." (PMID 39682281, 2024). "At a lower pHe, SIRT3 interacts with and activates CAVB, which converts the CO2 produced by the TCA cycle and β-oxidation to HCO3−, concurring to maintain the tumor pH gradient." (PMID 38931477, 2024). "SJ-106C, while still inhibiting SIRT1and SIRT2, is enriched in the mitochondria to help with SIRT3 inhibition.It is more active against DLBCL than other solid tumor cells and effectivelyinhibits DLBCL xenograft tumor growth." (PMID 39191393, 2024). "Nonetheless, SIRT3 deacetylates the oncogene Lon protease-1 (LONP1) to reduce the energy supply of OXPHOS, which restrains primary tumor growth, highlighting its context-dependent roles in carcinogenesis." (PMID 38773972, 2024). "The overexpression of SIRT3 inhibits Akt phosphorylation, leading to the degradation of the oncoprotein c-MYC via ubiquitination, which is crucial for tumor suppression." (PMID 39796040, 2024). "Therefore, the role of SIRT3 in tumor may be related to genetic background and environment." (PMID 38773972, 2024). "SIRT3 and SIRT4 suppress oncogenic pathways by regulating cancer metabolism, while SIRT2 and SIRT6 influence tumor aggressiveness and androgen receptor sensitivity, with SIRT6 promoting metastatic potential." (PMID 39796040, 2024). "Other genes were modulated in a different way in all three SCCs (NMNAT1, NMNAT2, NADSYN1, SIRT3, and CD38) or in two tumor types (NNMT, NMNAT3, ENPP2, PNP, and SIRT1)." (PMID 38254798, 2024). "SIRT3, a crucial regulator of mitochondrial redox, mitigated the augmented oxidative stress induced by miR-31 in OSCC, thereby promoting tumor cell migration and invasion in OSCC and enhancing the tumorigenic potential of FaDu cells." (PMID 38702756, 2024). "The varied roles of SIRT3, SIRT4, and SIRT5 in metabolic adaptation and cancer are outlined, emphasizing their tumor suppressor or oncogenic nature." (PMID 38331199, 2024). "Conversely, the overexpression of Pfn1 restores SIRT3 levels, resulting in the destabilization of HIF-1α and subsequent suppression of tumor growth." (PMID 39682281, 2024). "In contrast, SIRT3 and SIRT4 primarily function as tumor suppressors by regulating cellular metabolism, cell cycle progression, and chromosomal stability, thereby counteracting tumorigenesis." (PMID 39796040, 2024).